INS (insulin)
Diseases named in the same sentence as INS in open-access papers (continued):
Sharing a sentence is not in itself a finding about the gene and the disease.
diabetes (continued). "If insulin is excessive, insulin receptor sensitivity can be reduced, thereby reducing the ability to process glucose that is called non-insulin-dependent diabetes mellitus." (PMID 25177729, 2014). "Significant relationships were seen with baseline daily insulin doses (P < 0.001) and duration of diabetes (P < 0.05)." (PMID 24578756, 2014). "Specifically, in the UK evaluation by Hippisley-Cox and colleagues, diabetes status was determined through a read code for diabetes or a current prescription for anti-hyperglycemic agents or insulin from electronic medical records." (PMID 24460622, 2014). "Type 1 diabetes mellitus (T1DM), once known as insulin-dependent diabetes mellitus (IDDM), is an autoimmune disorder caused by progressive destruction of insulin-producing pancreatic β-cell that results in hyperglycemia." (PMID 25389531, 2014). "Insulin treatment rearranged the microbiota of the ileum so that it became very distinct from both the control and the diabetes populations." (PMID 25469509, 2014). "Several hypoglycemic agents that increase the insulin sensitivity, such as metformin, gliclazide and glitazones are currently being used to normalize glucose metabolism in diabetes treatment." (PMID 24993916, 2014). "The primary treatments for the type 2 diabetes mellitus patients were: metformin (68%; n = 16), a secretagogue (28%; n = 7), insulin (5%; n = 1), and an antihypertensive (36%; n = 9)." (PMID 25530952, 2014). "Our results suggest that it is necessary to improve diabetes management and optimize insulin therapeutic regimens in patients with T1D in Brazil to achieve HbA1c levels within the established targets." (PMID 24920963, 2014). "In this study context, insulin use tends to be an indicator for longer duration and greater severity of diabetes." (PMID 25184511, 2014). "This metabolic inflammation is characterized by a moderate excess in cytokine production, including interleukin (IL)-6, IL-1, or tumor necrosis factor alpha (TNF-α), that injures cellular insulin signals and contributes to insulin resistance and diabetes." (PMID 24808896, 2014). "This study shows that drinking the sour tea and green tea infusions, 3 times per day for 4 weeks, has different effects on the insulin resistance and certain lipoprotein in patients with type 2 diabetes mellitus." (PMID 25242840, 2014). "For example a team comprised of a nurse and a pharmacist can support insulin initiation for a poorly controlled patient with diabetes thereby avoiding the referral to a specialist endocrinology clinic." (PMID 24490703, 2014). "Our results put the loss of Ucn3 expression as an early event in β cell stress, occurring at the compensatory stage, before reduction in insulin expression and deterioration to frank diabetes." (PMID 25233132, 2014). "In particular, SMS reminders are a simple and cost-effective way to improve nonattendance; and provided an ubiquitous, easy-to-use, and cost-efficient solution to assist diabetes patients on intensive insulin treatment." (PMID 25099368, 2014). "Approximately 23% of patients had been diagnosed with diabetes and were prescribed oral hypoglycaemics and/ or insulin." (PMID 25361884, 2014). "This group of patients experienced a slightly worsening of beta cell function and insulin sensitivity starting ∼5 years before they were diagnosed with diabetes." (PMID 24523667, 2014). "Hypoglycemia is a common medical problem in patients with diabetes mellitus treated with insulin or insulin secretagogues." (PMID 24934576, 2014). "Of the 920 patients, 76 (8.3%) were taking oral hypoglycemic agents or receiving insulin replacement for control of diabetes mellitus, 102 (11.1%) lipid-lowering agents, 142 (15.4%) antihypertensives, and 159 (17.3%) hypnotics drugs." (PMID 25119532, 2014). "WHR was significantly associated only with duration of diabetes (p < 0.05) and WHtR was significantly associated with age (p < 0.05), management of diabetes by OHA (p < 0.05) and insulin (p < 0.05)." (PMID 25113234, 2014).
diabetes (continued). "The possible mechanism to developing diabetes mellitus among snorer was thought to be through insulin resistance via elevated sympathetic tone and intermittent hypoxia." (PMID 25883736, 2014). "Type 2 diabetes mellitus (T2DM) is a chronic disease characterized by hyperglycemia due to multiple dysfunctions including inadequate insulin secretion, resistance to insulin action, and excessive and inappropriate glucagon secretion." (PMID 24918743, 2014). "A sensitivity analysis in which we excluded 139 people who reported taking diabetes medication or insulin, or who reported being diagnosed with diabetes by a doctor, showed substantial similarity in point estimates, albeit with slightly larger CIs." (PMID 24891020, 2014). "Diabetes mellitus type 1 (DM1) is an autoimmune disease that gradually destroys insulin-producing beta-cells." (PMID 25157497, 2014). "The majority of diabetes is type 2 diabetes, which is featured by defects in both pancreatic insulin secretion (beta-cell dysfunction) and peripheral insulin action (insulin resistance)." (PMID 25628604, 2014). "Diabetes mellitus is characterized by a decline in β cell mass and function leading to insufficient insulin secretion and hyperglycemia." (PMID 24366643, 2014). "Diabetes mellitus is characterized by hyperglycemia resulting from defects in insulin secretion, insulin action or both." (PMID 24673913, 2014). "In this study, we evaluated KDT501 in various in vitro and in vivo models of diabetes and insulin sensitivity." (PMID 24498211, 2014). "We considered established diabetes risk factors: smoking, daily fruit and vegetable intake, participation in exercise, family history of diabetes, glucose values and BMI scores on post-partum re-screens, use of insulin during pregnancy, and age at delivery." (PMID 24461045, 2014). "The mean HbA1c of people with T2D prior to starting insulin is 9.4% (79.2 mmol/mol) in Australia (after a median diabetes duration of 8.1 years), and 9.3% (78.1mmol/mol) in the UK, well above recommended targets." (PMID 24528528, 2014). "Correlation analyses to determine the association between glycated albumin and other variables including insulin secretory indices and the duration of diabetes." (PMID 25265016, 2014). "Hypoglycemia is common in people with diabetes treated with insulin or oral medications such as sulphonylureas or other secretagogues, and constitutes a relatively rare paraneoplastic syndrome in patients with a variety of mesenchymal or epithelial tumors." (PMID 29147406, 2014). "Recent advances in insulin regimes and diabetes-related technologies have significantly reduced the occurrence of extreme forms of growth alteration in children and adolescents with T1D." (PMID 24648838, 2014). "These comparisons provide new directions to investigate physiology of insulin exocytosis in health and potential dysfunction as a pathophysiologic mechanism of diabetes mellitus." (PMID 25705631, 2014). "As expected, diabetes duration was significantly longer in insulin-treated patients (13.5 ± 9.8 years versus 6.8 ± 5.0 in patients on oral hypoglycemic drugs versus 1.7 ± 1.2 in diabetics not receiving any antidiabetic drug, p = 0.001)." (PMID 24934236, 2014). "Beta cell stress can contribute to diabetes development through increased antigen expression, whereas a reduction of diabetes incidence is seen in animal models with early prophylactic insulin treatment of diabetes-prone animals." (PMID 24871322, 2014). "The subsequent step is impaired early insulin secretion, leading to post-prandial and later, fasting hyperglycemia, at which time clinical diabetes becomes manifest." (PMID 25241606, 2014). "By contrast, insulin treatment significantly attenuated diabetes-induced hyperglycemia (350 ± 51 vs. 508 ± 43 mg/dl, P < 0.05), and hypoinsulinemia (1.66 ± 0.41 vs. 0.61 ± 0.10 μg/l, P < 0.01)." (PMID 25223305, 2014).
diabetes (continued). "Diabetes mellitus is characterized by reduced insulin signaling in cells resulting from insulin resistance (hallmark of type 2 DM) or lack of insulin secretion (hallmark of type 1 DM) or a combination of both mechanisms." (PMID 25309512, 2014). "Approximately half of these participants (ten in total) were taking only oral diabetes medication, whilst the remainder were taking insulin exclusively or in combination with oral diabetes medication." (PMID 24886191, 2014). "Overall, the subjects had a long duration of diabetes and poor glycemic control with large dosage of insulin." (PMID 24650537, 2014). "On the other hand, it was found that inhibition of C-jun N-terminal kinase improves insulin sensitivity in experimental diabetes." (PMID 25215302, 2014). "Six patients (16.7%) had a history of diabetes mellitus; five of them received oral hypoglycemic agents, one of them had regular insulin injections." (PMID 25047006, 2014). "In KPDM patients, the best predictors of insulin discontinuation are (i) presenting with new-onset diabetes and (ii) maintaining higher β-cell function reserves (as measured by the C-peptide-to-glucose ratio)." (PMID 25275325, 2014). "Administration of multiple low doses of streptozotocin resulted in severe insulitis, marked destruction of beta-cells, depletion of pancreatic and plasma insulin, elevation of glucagon and severe diabetes." (PMID 24967820, 2014). "In the early stage of diabetes development, the response of pancreatic islets challenged by nutrients and/or insulin resistance is a hypersecretion of insulin to maintain normoglycaemia." (PMID 24812634, 2014). "One DNE viewed GPs as knowing a little about a lot with little knowledge about diabetes management and insulin, and slow to take up management advice." (PMID 24479762, 2014). "Health professionals most commonly involved in insulin initiation in Australia include general practitioners (GPs), diabetes nurse educators (DNEs) and specialist physicians." (PMID 24479762, 2014). "Type 2 diabetes mellitus (T2DM) is commonly associated with obesity and results from defects in insulin secretion and/or diminished sensitivity of target tissues to insulin action." (PMID 24741571, 2014). "There are two pathophysiological components of feline diabetes mellitus: (i) reduced insulin secretion from dysfunctional and/or lost pancreatic beta cells, and (ii) insulin resistance, making this disease analogous to type 2 diabetes mellitus in humans." (PMID 25279695, 2014). "Increased levels of activin A in GDM patients has been reported in previous studies with a decrease to normal range after starting insulin therapy for diabetes treatment." (PMID 24763182, 2014). "Another signaling pathway that is activated by insulin in diabetes is the mitogen-activated protein kinases (MAPK) pathway viathe small GTPase Ras." (PMID 24734227, 2014). "In people with type 2 diabetes (the commonest type of diabetes), blood sugar control fails because the fat and muscle cells that normally respond to insulin by removing excess sugar from the blood become less responsive to insulin." (PMID 24845081, 2014). "Progressive loss of the insulin secretory capacity of the pancreatic beta cells and insulin resistance are the two mechanisms involved in the pathophysiology of type 2 diabetes mellitus (T2DM)." (PMID 25260374, 2014). "Given the structural and functional correlations between IGF1 and insulin, as well as the fact that both hormones employ identical signaling mediators, it is necessary to focus on the impact of obesity and diabetes on endometrial cancer." (PMID 24904527, 2014). "In patients with diabetes, β-cells slowly die, and this leads to a poor insulin response and an imbalance in the amount of fats and sugars in the cells." (PMID 25339419, 2014). "In summary, several previous studies have shown that in obese humans, circulating endocannabinoid levels and components of the ECS in adipose tissue are altered by insulin or diabetes." (PMID 24593280, 2014).
diabetes (continued). "It is promising in therapy application because it can increase the activity of insulin and slow down the development of diabetes mellitus." (PMID 25054160, 2014). "Obviously if these studies were to identify a molecule able to suppress hyperglycemia in an insulin-independent fashion, then, this molecule has the potential to lower hyperglycemia in both forms of diabetes and lengthen lifespan of diabetic people." (PMID 24589844, 2014). "SFRP4 has been shown to regulate insulin exocytosis and is overexpressed in type 2 diabetes mellitus." (PMID 25408147, 2014). "Reduced insulin sensitivity is an independent predictor of type 2 diabetes mellitus, hypertension, coronary heart disease, stroke and cancer in non-obese middle aged men15." (PMID 24503677, 2014). "Diabetes mellitus is a group of metabolic diseases in which hyperglycaemia results from defective insulin secretion, insulin action, or both." (PMID 24649368, 2014). "The current study measured the body composition in adults with newly diagnosed type 2 diabetes mellitus and explored the effect of metformin therapy on various components of body composition, insulin sensitivity, and glucose homeostasis." (PMID 25247153, 2014). "All patients were diagnosed with diabetes during youth or adolescence (13–24 years), and they have been treated with insulin, oral hypoglycaemic agents, and in some cases solely with diet." (PMID 25423173, 2014). "Only the odds ratios for age, sex, diabetes duration and insulin use are shown for the models conducted for age ≥40 years because the odds ratios for other variables are similar to those observed in the analyses for all ages." (PMID 24991802, 2014). "Both processes denote insulin sensitivity and decrease the need for insulin by patients with type 2 diabetes mellitus." (PMID 24576381, 2014). "PPAR agonists are insulin-sensitizing agents marketed for the treatment of type 2 diabetes mellitus that can improve endothelial function and inhibit the development of atherosclerosis." (PMID 25371664, 2014). "Five patients suffered from diabetes mellitus at time of the blood draw, and four of these were insulin-dependent." (PMID 25285204, 2014). "The relationship between plasma amylin and cognitive function disappeared among those with diabetes regardless insulin treatment." (PMID 25750761, 2014). "Glibenclamide therapy also prevented the diabetes-induced changes in insulin and glucagon staining, and in the area of individual islets, or whole pancreas, composed of ins+ and glu+ cells." (PMID 25145789, 2014). "Potential plausible molecular explanations for statin-induced diabetes include impairment in insulin secretion and exacerbation of insulin resistance." (PMID 25122464, 2014). "Another example is diabetes mellitus; prior to the introduction of insulin in 1922, patients with diabetes mellitus were considered to have a worsened pregnancy prognosis." (PMID 24552439, 2014). "Diabetes was controlled with oral hypoglycaemic agents alone in 55 (68.8%) patients, insulin in 4 (5%) patients, and a combination of oral hypoglycaemic agents and insulin in 21 (26.3%) patients." (PMID 25587544, 2014). "The rsT2DM group had the greatest improvement in insulin sensitivity which coincided with remission of diabetes." (PMID 25539584, 2014). "The ectopic accumulation of fat at these organs would result in steatohepatitis, insulin resistance, compression of the kidneys and therefore hypertension, diabetes, hyperuricemia and unfavorable renal hemodynamic pattern, which contribute to CKD." (PMID 24663403, 2014). "In this study, the insulin response to glucose was blunted in all pancreatectomized patients, and six developed overt diabetes mellitus during puberty." (PMID 24840042, 2014). "All of our patients had serious comorbidities (ischemic heart disease, high blood pressure), first and third patient was extremely obese and suffered from diabetes on insulin therapy." (PMID 25103782, 2014).
diabetes (continued). "For the treatment of type 1 and type 2 diabetes mellitus cartridges of Technosphere insulin (TI) should be used with an inhaler before taking meal." (PMID 26556194, 2014). "The effects of insulin treatment in islet transplantation in studies using STZ diabetes models are inconsistent." (PMID 24743240, 2014). "The purpose of developing a world wide web accessible glucose-insulin simulator has been to provide an educational opportunity for as many people as possible (patients with diabetes, their relatives, students, and HCPs)." (PMID 24511312, 2014). "It is estimated that, at the time of T2DM diagnosis, 50% of insulin production is already lost (U.K. prospective diabetes study 16 1995)." (PMID 24872354, 2014). "RESV has been the object of several diabetes studies because of its ability to improve insulin sensitivity, protect pancreatic β cells, and control glycaemia." (PMID 24218232, 2014). "Nitric oxide plays an important role on insulin's vasodilator effect as well as in states of insulin resistance, such as obesity and diabetes, characterized by reduced insulin-mediated vasodilatation subsequent to endothelial dysfunction." (PMID 25036223, 2014). "Despite recent advances in diabetes therapy including the new insulin analogs, insulin intensification strategies and newest therapeutic technologies such as continuous glucose monitoring system (CGMS) many patients fail to reach or maintain target HbA1c." (PMID 25275650, 2014). "Given the growing prevalence of T2D and the limited availability of these diabetes specialist resources making insulin initiation and titration part of routine primary care practice is necessary for uncomplicated diabetes." (PMID 25361788, 2014). "Although the benefits of oral Mg supplementation on glycemic control have yet to be demonstrated in diabetes patients, Mg supplementation has been shown to improve insulin sensitivity." (PMID 25013896, 2014). "The subjects with metabolic syndrome were comparatively older, more overweight or obese, hyperglycemic, insulin resistant and suffering from diabetes for longer duration." (PMID 25469328, 2014). "As aberrant immune responses and probably viruses are involved in pathogenesis of insulin dependent diabetes mellitus they studied oral insulin as self-antigen in transgenic mouse model to treat virus-induced insulin dependent diabetes mellitus." (PMID 26556194, 2014). "With more regular insulin supplies and the provision of an HbA1C machine donated through the International Diabetes Federation, it is expected that, coupled with ongoing diabetes education, glycaemic control in this population will improve." (PMID 25767657, 2014). "In fact, hyperinsulinemia, which is an excessive level of insulin in the blood, is often seen in several metabolic diseases, such as Type 2 diabetes mellitus." (PMID 24795642, 2014). "These mice are insulin resistant and develop diabetes as a result of impairment in survival and function of pancreatic β-cells." (PMID 24574966, 2014). "In the WHO model list of essential medicines, fast acting and intermediate acting insulin as well as a biguanide (metformin; as an insulin sensitizer) and a sulfonylurea derivative (gliclazide; as an insulin secretagogue) are selected for diabetes management." (PMID 25259517, 2014). "While specialist diabetes services have a role in managing complex cases, initiating insulin in routine general practice has several benefits." (PMID 24528528, 2014). "One hundred and forty seven (50%) reported insulin use either as a monotherapy or in combination with other medications for diabetes management." (PMID 24524353, 2014). "We propose that the molecular events associated with IR should be integrated to obtain a better understanding of the insulin signaling pathway and diabetes." (PMID 24633815, 2014). "Users of insulin and analogues had longest diabetes history (median duration 12 years, IQR, 8–18), followed by combination therapy users (7 years, IQR, 4–9)." (PMID 25369331, 2014).